CCL3 (C-C motif chemokine ligand 3)
Diseases named in the same sentence as CCL3 in open-access papers (continued):
Sharing a sentence is not in itself a finding about the gene and the disease.
infection (continued). "The infection of human macrophages induced the expression of pro-inflammatory cytokines/chemokines such as MCP-1/CCL-2, IFN-α2, IFN-γ, MIP-1α/CCL-3, IP-10/CXCL-10, RANTES/CCL-5, IL-8, TNF-α, IL-12p40, and IL-6." (PMID 30984127, 2019). "Several differentially expressed genes identified in our study (i.e., ADIPOQ, CCL3) are related to tumor necrosis factor (TNF), a cytokine that produces an immune response to help prevent the spread of infection." (PMID 31788200, 2019). "We found increased levels of IL-1β, CCL2, and CCL3 concomitant with elevated neutrophil infiltrates in the CSF of animals with S. epidermidis-infected catheters, which may serve as potential markers for distinguishing infection from sterile postoperative inflammation in humans." (PMID 31262978, 2019). "Furthermore, in an intraperitoneal infection model, Dectin-1 knockout mice were less able to recruit neutrophils, monocytes, and eosinophils to the site of infection than wild-type mice and this was associated with a decrease in IL-6, CCL2, CCL3, G-CSF, and GM-CSF production." (PMID 32047726, 2019). "While IL-1α and IL-1β levels in WT and IL-1R−/− mice were similar, levels of IL-6, IL-12p70, IFN–γ, CCL2, CCL3, and CXCL9 were significantly lower in IL-1R−/− mice compared with wild-type mice following infection with P1/7 (p < 0.05)." (PMID 31262357, 2019). "Infection with the ΔgliP mutant significantly stimulated the expression of CXCL2, CCL3, CCL4, CCL7, TNF-α, and IL-6, whereas infection with the Δaspf1 ΔgliP double mutant significantly decreased the expression of CXCL2, CCL7, TNF-α, and IL-6." (PMID 30052103, 2018). "Especially the chemokines CCL3, CCL5, and CCL11 increased in the lower infection groups 3 months after treatment." (PMID 30619332, 2018). "CCL2, CCL3, and CCL5 belonging to inflammatory chemokines, are produced in high concentrations during infection or injury and determine the migration of inflammatory leukocytes into the damaged area." (PMID 30480097, 2018). "Although mRNA levels of all these cytokines reduced in RV-infected mice with COPD phenotype, the levels of CXCL-1, CXCL-10, CCL3, TNF-α, IL-17A and IFN-γ remained high up to 14 days post-infection." (PMID 29975735, 2018). "At day 6 post-infection, C57BL/6J mice also exhibited higher levels of IL1A, IL1B, CCL2, CCL3, IL2, IL10, and IL6." (PMID 30713529, 2018). "The receptors that bind the main chemokine attractants of monocytes (CCR1 for CCL3 and CCR2 for CCL2) that mediate monocyte recruitment to sites of infection were equally expressed on the monocytes of the three groups." (PMID 29116124, 2017). "Analysis of mRNA levels of IL-6 and other pro-inflammatory cytokines and chemokines at 2.5 h, 4 h and 8 h post infection (p.i.) revealed a moderate induction of IL-6, TNFα, CCL3 and CCL5 upon IV infection of Calu-3 cells." (PMID 28195157, 2017). "Further, although we did not observe significant differences in monocyte recruitment to the footpad, CCL3, CCL4, CCL7, and CXCL10 are all known monocyte chemoattractants that were also significantly reduced during Opal524R infection." (PMID 29138302, 2017). "In response to infection with hRSV, human AEC-derived cell lines secrete cytokines and chemokines in vitro, including IL-6, IL-8, CCL2, CCL3, and CCL5 that promote the recruitment of monocytes and eosinophils to the site of infection." (PMID 29230219, 2017). "Optimal expression of Ccl2, Ccl3, Ccl4, and Cxcl1 depends on DDR signaling in macrophages, and these chemokines regulate the migration of innate immune cells during infection." (PMID 28362262, 2017). "The levels of MIP1α/Ccl3, IL-1, and IFNγ-inducible factors, such as ICAM-1, IP10/Cxcl10 and Cxcl9 were all increased in the chronic phase of the infection." (PMID 28787450, 2017). "We have previously shown that decidual cell culture supernatants, which contain CCL3 and CCL4, partially inhibit the infection of decidual mononuclear cells by blocking the HIV-1 entry." (PMID 27267272, 2016).
infection (continued). "As well as participating in the innate immune response, CCL3 and CCL5 also function in cell-mediated adaptive immunity as they both attract T lymphocytes to sites of infection and they preferentially recruit T helper (Th) type 1 differentiated cells." (PMID 27479136, 2016). "The O175A and O265B reassortant viruses produced similar secretome profiles, and in both of these samples the levels of proinflammatory mediators TNF-α, CCL3, and CCL5 were lower than those resulting from WT PR8 infection." (PMID 27489273, 2016). "Infection of epithelial cells by IFV increases the expression of TNF-α, IL-6, IL-8, CCL2 (MIP-1), CCL5 (RANTES), CCL3 (MIP-1α), and CXCL10 (IP-10)." (PMID 28066442, 2016). "In this study, total spleen cells were shown to secrete TNF-α, IFN-γ, IL-6, IL-10, CCL3, and CXCL9, suggesting an activation of splenic cells during the infection and a polarization towards a Th1 response." (PMID 27905502, 2016). "Infection activates a broad chemokine response to infection, including CXC (CXCL1, CXCL5, CXCL8, CXCL9, and CXCL10) and CC chemokines (CCL2, CCL3, and CCL5)." (PMID 26927188, 2016). "Upon infection, they initiate inflammatory responses by releasing cytokines and chemokines, such as IL-1β, IL-18, TNF-α, and CCL3." (PMID 27043315, 2016). "Preceding the influx CD3+CD8+ T-cells in this model was an increase in Th1-type chemoattractants CXCL9, CXCL10, CCL3 and CCL5 at peak primary infection." (PMID 27467505, 2016). "CCL3 and CCL4 are kept at the low levels until induction by inflammation or infection, but, in addition to being inducible by inflammatory and disease conditions, CCL18 is constitutively expressed at high levels in certain tissues." (PMID 25636406, 2015). "Macrophage inflammatory protein-1 (MIP-1α/CCL3), which was highly expressed in our retinal pericytes after infection, would serve to heighten the inflammatory microenvironment to establish a persistent inflammatory state." (PMID 25573478, 2015). "The expression of chemokines CCL3, CCL4 and CCL5 was reported during the acute and chronic stages of infection by T. cruzi." (PMID 26599761, 2015). "Elevated levels of secreted CCL3 (MIP-1α), CCL4 (MIP-1β) and CCL5 were observed following infection of human mast cell lines." (PMID 26462910, 2015). "These cytokines are important for the activation of chemokines (such as MIP-1α/CCL3 and MIP-1β/CCL4) involved in leukocyte recruitment to the infection site for effective pathogen eradication." (PMID 26316174, 2015). "The induction of a set of chemokine genes (CCL3, CCL4 family) with a common receptor (CCR5) is also very intriguing and suggests that the effect of infection of XMLV in Raji cells is immunomodulatory." (PMID 25912714, 2015). "The percentage of IFN-γ+CD3+ T cells and IL-17+CD4+ T cells in spleen, as well as the levels of IFN-γ, IL-17A/F and CCL3 in spleen and lung, significantly increased in the MAP27-immunized mice after infection." (PMID 26317210, 2015). "In contrast, there was a striking expression of the Th1-related chemokine receptor CCR5 in the ileum and liver of infected mice, as well as the chemokine ligands for this receptor CCL3 (MIP-1α), CCL4 (MIP-1β) and CCL5 (RANTES) at 8 days post infection." (PMID 25119429, 2014). "Further chemokine gene expression studies in brains of ECM-susceptible mice confirmed that CXCL10, CXCL9 and CCL5 and to lesser extent CCL2, CCL7, CCL3, CCL4 and CXCL2 are upregulated during infection with P. berghei ANKA." (PMID 24476686, 2014). "Similar to this study, we observed significant up-regulation chemokines and cytokines, such as CCL3, CXCL10, IL1RN, IL6 and TNF, throughout infection." (PMID 25079789, 2014). "The results were consistent with mRNA findings, as large amounts of the CC chemokines CCL3, 4, 5, and 7 and, particularly, of the CXC chemokines CXCL9, 10, and 11 were observed 24 and/or 72 h after the infection of MP with MOPV." (PMID 24421914, 2014).
infection (continued). "Ccl3, Ccl5, Tnfa, and Il6 were expressed at modest levels in unprimed RAW 264.7 cells upon infection, whereas pre-treatment of cells with IFN-γ strongly enhanced HSV1-induced gene expression." (PMID 25268627, 2014). "Microarray analysis revealed that the expression of CCR5, CXCR3 and CCR1 and several of their chemokines including CXCL9, CXCL10, CCL2, CCL3 and CCL9 significantly increases in response to infection in CM-affected mice." (PMID 24476686, 2014). "In the early phase of the infection, cellular antiviral immunity is initiated by Kupffer cells releasing CCL2, resulting in the recruitment of CCL3-producing monocytes and pDCs, which attract NK cells." (PMID 24646914, 2014). "CCL3 and CCL4 recruit NK cells to the site of infection, where they are activated by IL-12 and exert antiviral activity by secretion of IFN-γ." (PMID 24646914, 2014). "Genetic analysis of F2 hybrids has revealed identical genetic control of serum levels of CCL3 and CCL5 at week 7 after infection." (PMID 23875032, 2013). "Elevated levels of CCL3, CCL4, CCL5 and CXCL9 mRNA were detected in the livers of both WT and WSX-1−/− mice on day 7 of infection, whereas CCL3, CCL4, CCL5 and CCL20 mRNA levels were increased on day 14 of infection." (PMID 24244314, 2013). "In the lethal infection, CCL11, interferon-γ, and CCL3 each strongly correlated with worsening clinical symptoms, including weight loss, diminished oxygen saturation, and increasing Penh." (PMID 24359540, 2013). "Cytokines and chemokines such as CCL2 (MCP-1), CCL3 (MIP1α), CCL5 (RANTES), and CXCL10 (IP10) are responsible for activating leukocytes and attracting them to the lung compartment to clear infection." (PMID 23441208, 2013). "In the lethal infection, levels of CCL11, interferon- γ and CCL3 all correlated strongly with disease severity." (PMID 24359540, 2013). "Addition of Bb induced up-regulation of transcript levels for all chemokines assessed, including CXCL1, CXCL2, CCL2, CCL3, CCL4, and CCL5 by MØs and DCs as early as 4h post-infection." (PMID 24367705, 2013). "An up-regulation of Ccl3, Ccl4, Ccl5, and Tgfb, a strong CD4+ T-cell response, and down-regulation of Il17, Il21 and Il23 occurred during infection." (PMID 23383148, 2013). "IEC isolated from neonates at the peak of the infection presented a clear up-regulation of XCL1, CCL3, CCL4, CCL5, CXCL9, and CXCL10 expression, with levels close to those in adults for CXCL9 and CXCL10." (PMID 24367259, 2013). "Airway levels of CXCL1, CCL2, CCL3, CCL5, IFNγ, IL-6, and TNFα were measured 3 and 6 days after infection." (PMID 22496659, 2012). "Rather, RTD-1 administration appeared to protect infected animals by reducing pulmonary inflammation and suppressing IL-1α, IL-1β, IL-6, IL-12, CXCL1 (KC), CCL2 (MCP-1), CCL3 (MIP-1α), and CCL5 (RANTES) 2–4 days post-infection." (PMID 23236475, 2012). "Some others such as CCL3, CCR5, CXCL9, CXCL10, CX3CR1 and CCL24 showed a low expression during the infection." (PMID 22905138, 2012). "One study showed that infection of mice with L. major upregulated the gene expression of several chemokines (RANTES/CCL5, MIP-1α/CCL3, IP-10/CXCL10, and MCP-1/CCL2) in cells collected from the footpad and their draining lymph nodes." (PMID 22131998, 2012). "Consistent with previous studies and associated with the classical activation M1 phenotype, transcription of TNFα (up to 5), CXCL10 (IP10), CCL2 (MIP1α), and other chemotactic cytokines such as CCL3 (up to 6.8) and CCL4 was upregulated following infection." (PMID 22928052, 2012). "During the experimental infection of macaques with CHIKV, we observed an early induction of IFN-α, MCP-1/CCL-2, and IL-6, followed by the detection of MIP-1α/CCL-3 and MIP-1β/CCL-4, IFN-γ, and TNF-α." (PMID 22479654, 2012). "In vitro infection of immature dendritic cells (imDC) with DENV-2 led to induction of CCL11/Eotaxin, CCL2/MCP-1, CCL5/RANTES, CCL3/MIP-1α and CXCL10/IP-10." (PMID 22815692, 2012).
infection (continued). "Numerous studies have demonstrated that these cytokines are important to activation of chemokines (such as MIP-1α/CCL3 and MIP-1β/CCL4) involved with the leukocyte recruitment to the infection site for effective pathogen eradication." (PMID 21473761, 2011). "Disease associated with highly pathogenic influenza viruses and the clinical manifestations that ensue in humans can be mediated by the proinflammatory response (e.g., TNF-α, IL-6, CCL2, CCL3, and CXCL10) initiated by the host in response to infection." (PMID 21829352, 2011). "Such subepithelial pDCs are recruited and produce IFNα, IFNβ, MIP-1α (CCL3), and MIP-1β (CCL4) at day 1 of infection, which in turn promote inflammation and recruit T cell targets for infection." (PMID 21852945, 2011). "In contrast, in X4LAI.04-infected tissues production of CCL3, CCL4, CCL5, CXCL10, and CXCL12 was significantly increased compared with that in uninfected tissues and reached a maximum 5 to 9 days post-infection." (PMID 20862220, 2010). "In X4LAI.04 infected tissues treated with flagellin, there was a significant increase in the levels of CCL3, CCL4, and CXCL10 (by 130%, 60%, and 30%, respectively; p<0.047, n = 6) already on day 3 post-infection." (PMID 20862220, 2010). "We also report here a small transient increase in CCL4 and CCL5 mRNA one day post L. major inoculation at the site of infection in C57BL/6 mice, but CCL3 clearly showed a much higher level of transcriptional induction in these mice." (PMID 20140197, 2010). "One study has found that infection with SHIV can lead to decreased levels of CCL3, CCL4, and CCL5 in PBMCs during the acute phase of infection." (PMID 19149556, 2009). "Following infection significant increases of CCL2 (MCP-1), CCL3 (MIP-1α), CCL4 (MIP1-β), CCL5 (RANTES) and CXCL9 (MIG) were observed in WT NOD mice compared to uninfected controls." (PMID 19122812, 2009). "Virally, stimulatedpDC produces chemokines, such as CCL3 (MIP-1a), CCL4 (MIP-1b), CCL5 (RANTES),CXCL8 (IL-8), and CXCL10 (IP-10) which stimulate Th1, and NK cells homing tosite of infection through IP-10 and CCL4, respectively." (PMID 19190769, 2008). "Infection of WT mice with rMA15 resulted in a significant induction of proinflammatory chemokines including CCL2 (MCP-1), CCL3 (MIP-1α), and CCL5 (RANTES) as compared to mock-infected control mice." (PMID 19079579, 2008). "By PID 180, expression of CC-chemokines returned to pre-infection levels (CCL4 and CCL5), or even increased (CCL3)." (PMID 17684570, 2007). "At the chronic stage of SHIVSF164P4 infection, expression of the CCR5 ligands returned to pre-infection levels (CCL4 and CCL5), or even increased (CCL3) in all three GALTs." (PMID 17684570, 2007). "These levels were significantly lower (p<0.005 for CCL3; p<0.05 for CCL4 and CCL5) than those prior to infection." (PMID 17684570, 2007). "When the vaccine proteins were targeted toward chemokine receptors 1, 3, and 5 (CCR1/3/5) on APC by means of macrophage inflammatory protein 1-alpha (MIP1α) (CCL3), vaccinated mice were broadly protected against infection with H1N1, H3N2, H5N1, and H7N1 influenza viruses." (PMID 41568167, 2026). "CCL3 has also been shown to reduce infection and promote wound healing in nondiabetic mice, underscoring its potential as a novel therapeutic approach in wound care." (PMID 41597195, 2026). "Conversely, CpG sites related to Slc11a1, Havcr2, Ccl11, Ccl12, Sirt1, Ifng, Ccl3, Ror2, and Trem2 maintained lower methylation levels throughout the infection compared to noninfected samples." (PMID 40170749, 2025). "Moreover, an increased expression of macrophage inflammatory proteins (MIP1α, CCL3) and MIP2α (CXCL2) were found in bone samples of patients suffering from an infection of orthopedic prostheses." (PMID 40137369, 2025). "However, comparable levels of TNF, IL-6, IL-10, CXCL1, CCL3, GM-CSF, and G-CSF were observed upon CRWT and CRM12 infection." (PMID 40599135, 2025).
infection (continued). "The factors secreted by the parasite, during the chronic form of infection, stimulate the production of interleukin 12 from dendritic cells and macrophages, as well as the interaction between chemokines, such as CCL4, CCL5 and CCL3." (PMID 40855457, 2025). "For the other cytokines tested, including GM-CSF, IFN-α, and CCL3, no clear infection-induced transcription kinetics were observed, although a significant increase in expression was observed for IL-8 and M-CSF at 0 hpi." (PMID 41280933, 2025). "Moreover, only S- and S/N-immunized animals had reduced levels of CCL2, CCL3, CCL4 and CXCL10 chemokines after the infection compared to the PBS group." (PMID 41306976, 2025). "Additionally, chemokines such as CCL3 (MIP-1α), CCL4 (MIP-1β), and CCL5 (RANTES) aid in the recruitment of other immune cells to the site of infection." (PMID 40665369, 2025). "In the striatum, we also see clustering within the fentanyl-treated groups based on infection status: EcoHIV-infected mice treated with fentanyl had higher concentrations of CCL2, CCL4, CCL5, and CCL11 but lower levels of CCL3 and CXCL10 than the uninfected, fentanyl-treated animals." (PMID 40447886, 2025). "Six months post-infection, the levels of both CCL-3 and CXCL-13 were not elevated in either hospitalized or non-hospitalized individuals." (PMID 38646483, 2024). "Matching the data collected during the physical characterization of the NTHi-NHNE infection, expression levels of key chemo- and cytokines (e.g. CXCL8, IL-6, IL-1β, CCL3, CXCL1 & CXCL2) and genes involved in ECM remodelling and inflammation (PLAU, Serpine1, MMP9) increased further on day14." (PMID 38990812, 2024). "Additionally, CCL3, CCL4, and CXCL2 levels were low at day 14 and recovered by day 28 post-infection, also in agreement with our findings." (PMID 39044282, 2024). "In PCLS, where neutrophils are scarcely present, an increased expression of pro-inflammatory cytokines and chemokines related to neutrophil recruitment and activation such as CXCL1, CCL3, or IL-17A was measured, particularly in PCLS of old mice upon infection with D61." (PMID 38178102, 2024). "Furthermore, macrophage inflammatory proteins such as MIP-1α (CCL3) and MIP-1β (CCL4) play a major role in immune responses against infection or inflammation in response to external stimuli." (PMID 38494495, 2024). "Meanwhile, the expression of innate immune-related genes TNF-α, CCL3, and BAX was upregulated both by infection and fenofibrate at an early stage of incubation (4 h), with higher expression levels with the merge of infection and fenofibrate than by the two conditions separately." (PMID 38543516, 2024). "Furthermore, another study showed that human M1-activated monocyte-derived macrophages stimulated less CCL3/MIP-1⍺ and less TNF-α after infection with lactate-grown C. albicans compared to glucose-only-grown cells." (PMID 38967888, 2024). "Similarly, we observed significant increases in IL-17, G-CSF, CXCL1, CCL2, CCL3, CCL4, and CCL11 production in 5-LO−/− mice, compared to C57BL/6 mice, at day 7 post-infection." (PMID 39082787, 2024). "For example, mature DCs could produce CCL3 and CCL4 after Mtb infection, which further recruit immature DCs to the site of infection and replace the mobilized population." (PMID 36315280, 2023). "However, at 30 days post-infection, TNF-α, IL-6, KC, CCL3, CCL2, CCL20, CXCL11, CCL11), CCL27, CXCL5, CXCL12 and CCL5 were all significantly higher in the BAL fluid of Duox1 KO compared to WT mice." (PMID 36936954, 2023). "Our study also shows that trypomastigote lysate, OGE fractions and rTcMIP were all able to trigger IFN-γ, CCL2 and CCL3 responses by human umbilical cord cells, indicating that the immune-stimulating effect did not depend on cell infection." (PMID 37033946, 2023).